MMP9 (matrix metallopeptidase 9)
Diseases named in the same sentence as MMP9 in open-access papers (continued):
Sharing a sentence is not in itself a finding about the gene and the disease.
tumor (continued). "In view of the regulation of E-cad, MMP-9, MMP-2, and vimentin, the results showed that TPL/NPs effectively suppressed tumor metastatic effects in vivo." (PMID 34162396, 2021). "Crocin significantly inhibits tumour growth, and it also downregulates MMP2 and MMP9, which are involved in extracellular matrix degradation of tumour cells." (PMID 34256821, 2021). "It is well known that local invasion is the first requirement for distant metastasis, while a key event in tumor invasion is degradation of the surrounding ECM, which involves activation of MMP-2 and MMP-9 6,8." (PMID 34149918, 2021). "Both MMP9 and MMP13 have been shown to release active growth factors such as VEGF from the ECM to increase tumor angiogenesis." (PMID 33808627, 2021). "CCL2 and C-C motif chemokine ligand 17 (CCL17) support tumour growth by recruiting CD4+ Treg cells and macrophages, while VEGF and MMP-9 stimulate angiogenesis and tumour cells migration." (PMID 34769447, 2021). "TWIST is responsible for inducing the formation of actin-rich invadopodia, which recruit MMP7, MMP9, and MMP14 to the leading edge where they degrade ECM and basement membranes, facilitating tumor invasion and metastasis." (PMID 34943943, 2021). "In our study, secretion of IL-6, IL-8, MMP-9, PDGF-BB, IL-1β, G-CSF, and CCL-2 by ccRCC immune cells in tumor microenvironment were able to overcome the anti-angiogenic effects of cabozantinib." (PMID 34931665, 2021). "HP can be specifically recognized and cleaved by matrix metallopeptidase 9 (MMP9), which is highly expressed in tumor tissue, thereby opening the MSN channel to release the drug." (PMID 35053199, 2021). "Matrix metalloproteinase-2 (MMP-2) and matrix metalloproteinase-9 (MMP-9) degrade the extracellular matrix and basement membrane, correlated with tumor invasion and metastasis." (PMID 34065478, 2021). "MMPs lacking a transmembrane domain are expressed on the surface of other cells including MMP‐1 on keratinocytes, MMP‐2 on the surface of endothelial cells, fibroblasts, and tumor cells, and MMP‐8 and MMP‐9 on the surface of PMNs." (PMID 33656791, 2021). "KCs also secrete hepatocyte growth factor (HGF), VEGF, and matrix metalloproteinases (MMPs) such as MMP-9 and MMP14 that promote tumour cell invasion in the parenchymal space as well as tumour cell proliferation and angiogenesis." (PMID 33669775, 2021). "Given the critical function of MMP-2 and MMP-9 in tumor cell migration and invasion, we investigated the effect of sh-LINC00488 on the protein expression levels of MMP-2 and MMP-9." (PMID 33600548, 2021). "MMP2, MMP7, and MMP9 are members of the MMP family and are mainly involved in tumour invasion and metastasis." (PMID 33995637, 2021). "Evaluates the expression of angiogenic factors secreted by tumor cells, such as VEGF, bFGF, etc.Evaluates the expression of matrix metalloproteinases secreted by tumor cells, such as MMP-2, MMP-9, etc." (PMID 34746014, 2021). "In summary, the MIR4435-2HG/hsa-miR-1-3p/MMP9/hsa-miR-29-3p/DUXAP8 ceRNA network axis was constructed by using bioinformatical tools, and it might be closely associated with the development of HCC, associated with a poor prognosis in HCC patients, and associated with tumor immune cell infiltration." (PMID 35201491, 2021). "This generates invasion, metastasis, and angiogenesis of tumor through activation of VEGF, COX-2, MMP-9, and IL-8." (PMID 34220337, 2021). "In a 1,2-dimethylhydrazine-induced colon cancer rat model, treatment with piroxicam and C-PC resulted in a lower tumor expression of MMP-2 and MMP-9 compared to a control." (PMID 33498927, 2021). "Though, TCE has been found to inhibit mitogen-activated protein kinase (MAPK) and matrix metalloproteinase 9(MMP-9) pathway and decrease invasion and migration abilities of tumor cells." (PMID 33906308, 2021). "Similar to previous studies, SPP1, MTHFD2, TRIP13, MKI67, MMP9, and KLF4 were some of the most clinically valuable tumor markers, especially in CC and EC." (PMID 34834529, 2021).
tumor (continued). "To demonstrate the anti-proliferative and anti-metastatic role of CPEB1 in vivo, we examined the levels of immunoreactive Ki67, matrix metallopeptidase-9 (MMP-9), and E-cadherin in mouse tumour tissues by immunohistochemistry (IHC) and Western blotting (WB)." (PMID 33892791, 2021). "Recruitment of MMP-9 to the cell surface triggers TGF-β activation and fibroblast differentiation into myofibroblasts, which enhance tumor progression through stroma remodeling." (PMID 33807594, 2021). "Consistent with these, our results demonstrate that ZnPc-PDT with 12 J/cm2 or 24 J/cm2 irradiation can inhibit the tumor migration and downregulate the expression of ROCK1 and MMP9 in SW480 cells." (PMID 34833970, 2021). "Due to their structural and functional similarities, it is not surprising that multiple studies report co-upregulation of MMP-9 and MMP-2 upon irradiation, leading to increased tumor cell invasiveness, metastasis, and angiogenesis." (PMID 34055644, 2021). "Tumor cells mitigate the immune response by releasing MMP-2, MMP-9, MMP-13 and MMP-14, resulting in the inhibition of T-cell proliferation and antigen presentation." (PMID 34204372, 2021). "In vitro invasion assay confirmed that irradiation targeting D2A1 tumor and its microenvironment increased the levels of plasma IL-1β, promoted the infiltration of tumor cells and the development of lung metastasis and increased the activity of MMP-2 and MMP9." (PMID 34602858, 2021). "In the furthermore bioinformatics analysis, we found that MMP1, MMP3, MMP7, MMP9, MMP12, MMP13 all increased in the tumor as compared with the normal esophageal tissues." (PMID 34559117, 2021). "Since the MMP-9 gene is inducible in cancer cells and TGF-β-dependent induction of MMP-9 promoter is relevant in tumor cells displaying invasive potential, we used TGF-β and PMA as inducers to study the effects of FQs on MMP-9 activity." (PMID 34769032, 2021). "Through inhibiting MMPs such as MMP-9, MMST can recruit CXCR3-positive T cells to focus on tumor due to the increased chemokines in the TME, and then exhibit a synergistic effect with chemotherapeutics such as PTX to achieve chemoimmunotherapy." (PMID 34959271, 2021). "Several metalloproteinases such as MMP2, MMP3, MMP9 and MT1-MMP have been shown to be upregulated in lymph nodes or lung tissues distant from the primary tumor by tumor-derived exosomes." (PMID 33809973, 2021). "Among the down-regulated genes, GLI1 and some other tumor progression related genes were discovered, for example, MMP1, MMP9, NFKB2, TGFA, and EGFR." (PMID 33637972, 2021). "As we previously identified MMP9 as a novel agonist of protease‐activated receptor 1 (PAR1), a receptor that is known to orchestrate the cross‐talk between macrophages and tumor cells in PDAC, we here assessed the contribution of PAR1 to pancreatic cell fates." (PMID 33932087, 2021). "In this study, we found that Rbm24, PTEN and P21 mRNA levels were significantly downregulated in tumour tissues of Apcmin/+ mice compared to adjacent normal samples (N = 18); meanwhile, the expression levels of MMP‐2 and MMP‐9 were markedly elevated." (PMID 34709758, 2021). "Tumor invasiveness has been found to be mediated by the increased activation of matrix metalloproteinase-2 and -9 (MMP-2 and MMP-9), mediated by IL-8 levels, indicating that the IL-8 level is associated with metastatic invasiveness and early recurrence." (PMID 33912192, 2021). "MMP-9 is one of the MMPs and high MMP-9 expression in multiple tumors can stimulate tumor cells to move out of the carcinoma nest and promote tumor cells going in and out of blood vessels, thus enhancing invasion and metastatic abilities of tumors." (PMID 34059099, 2021). "Preclinical evidence suggests that SPARC deletion has stimulating effects on ischemic retinopathy, RNV and tumor angiogenesis by enhancing VEGF and MMP9 expression." (PMID 34795670, 2021).
tumor (continued). "On the other hand, MMP9 can activate the mitogen-activated protein kinase (MARK)/ERK and TGF-β/SMAD signaling pathways to further promote tumor metastasis." (PMID 34607974, 2021). "Namely, HSCs can modulate the ECM through secretion and upregulation of matrix metalloproteinases (MMPs), such as MMP2 and MMP9, both of which promote HCC tumor migration." (PMID 33791228, 2021). "Related studies have proven that MMP-2 and MMP-9 exist downstream of STAT3 and play an important role in tumours." (PMID 34222329, 2021). "Further, all non-tumoral adjacent tissues showed very low activity levels of both pro-MMP9 and pro-MMP2, whereas higher activity levels were detected in the paired tumor samples." (PMID 34830271, 2021). "Another study investigated the tumor-suppressive mechanisms of ACE2 via angiogenesis and tumor invasion, and found these to be mediated by regulation of MMP-2, MMP-9, and VEGFa." (PMID 33513805, 2021). "It increases the activity of matrix metalloproteinase 9 (MMP9), which breaks down the extracellular matrix and basement membranes, by preventing its autodegradation, and results in tumor progression, invasion, and metastasis." (PMID 33542838, 2021). "MMP-9 has been reported to cleave and potentially degrade T-helper cell 1 (Th1)-type chemokines like CXC ligand CXCL10 and inhibit their anti-tumor outcome, including the recruitment of CD4+ T cells and CD8+ T cells, and their tumor-killing effect." (PMID 34959271, 2021). "The transcription factor AP1, which consists of c-Jun and c-Fos, plays an important role in controlling MMP1, MMP9, and MMP12 expression in tumor cells." (PMID 33958583, 2021). "“Basal-like” subtype presents KRASG12D mutation, while “activated” stroma subtype expresses SPARC, WNT family members WNT2 and WNT5A, gelatinase B (MMP9), stromelysin 3 (MMP11), and FAP that contribute to tumor development." (PMID 33477288, 2021). "GBM cells produce different ECM components such as hyaluronic acid (HA), matrix metalloproteinase-2 (MMP2), matrix metalloproteinase-9 (MMP9), integrins, tenascin-C, and fibronectin to degrade and remodel the ECM for tumor invasion." (PMID 33670551, 2021). "In our study, ALX1 overexpression promoted tumor progression in EC at least partly through upregulation of MMP2, MMP9, VEGF and vimentin." (PMID 34104082, 2021). "TAM (M2) produce tumor growth and invasive factors such as growth factors (EGF and VEGF), cytokines, enzymes supporting the process of angiogenesis (MMP9), inhibit the expression of anti-cancer factors such as IL-12 and accumulate at hypoxic sites." (PMID 34526531, 2021). "The most interesting finding in this context is the continuously decreasing expression of MMP-9 and TIMP-1 at the invasive front of the tumor periphery in CDV-infected xenografts over time, which accompanied the decelerated growth of infected neoplasms." (PMID 33808256, 2021). "Similar to MMP-9, IR also induces upregulation of MMP-2 resulting in enhanced tumor growth and cell invasiveness." (PMID 34055644, 2021). "Moreover, we found increased levels of sE-CAD, FN, and MMP9 in the secretome of directionally migrating tumors, indicating that intrinsic hypoxic environment triggers directional migration and induces higher levels of tumor-secreted factors through the acquisition of mesenchymal features." (PMID 33804802, 2021). "This is observed through activation of the sirtuin 1 gene/AMPK (SIRT1/AMPK) signaling pathway, known as tumor suppressor genes, and inhibition of the expression levels of MMP2 and MMP9 in NSCLC cells." (PMID 34069141, 2021). "Results demonstrated a significant reduction in tumor size and the highest levels of IFN-γ and IL-17 and the lowest levels of IL-4 FoxP3, HIF-1α, VEGF, MMP-2, and MMP-9 in the IT+IP+TEX-treated group." (PMID 34194604, 2021). "On the other hand, the expression of metastatic tumor indicators, CD44v6, MMP-2, and MMP-9 decreased in A549 cells exposed to VPA." (PMID 34400947, 2021).
tumor (continued). "Since MMP-9 can degrade the extracellular matrix and basement membranes, LCN2 protects MMP-9 from degradation, thus increasing MMP-9 activity to contribute to tumor progression and metastasis through formation of an LCN2/MMP complex." (PMID 34202288, 2021). "In mouse colorectal cancer models, neutrophil-secreted MMP-9 activates latent TGFβ in the ECM by degrading the ECM, increasing the level of TGFβ in the tumor microenvironment, and thereby inhibiting antitumor T cell response." (PMID 34327245, 2021). "The expression of MMP-9 in CRC tissue is significantly higher in comparison to CA and normal mucosa, and correlates with tumor stage." (PMID 34071492, 2021). "Gelatinases, including metalloproteinase 9 (MMP-9) and metalloproteinase 2 (MMP-2), play an important role in the development of malignancies through facilitating tumor invasion, metastasis, growth, cell migration and angiogenesis." (PMID 34071492, 2021). "Intriguingly, remarkable suppression of Integrin α6, integrin ’β4, metastatic markers—vimentin and MMP-9, and enhanced cleavage of caspase-3 was observed in ATQ-treated tumor lysate." (PMID 34071408, 2021). "In vivo experiments further validated that lnc-KASRT enhanced tumor growth and reduced tumor apoptosis; meanwhile, it also increased tumor KLF6-SV1, MMP-1, and MMP-9 expressions but decreased tumor SRSF1 and KLF6-WT expressions in xenograft mice." (PMID 34568030, 2021). "The acidic tumor microenvironment can induce the expression of MMPs such as MMP-2 and MMP-9 and enhance the invasion and metastatic ability of tumor cells." (PMID 34976805, 2021). "Stimulation of angiogenesis is an additional role assigned to MMP-9, through its control over the availability of vascular endothelial growth factor (VEGF), which is essential for tumor neovascularization." (PMID 34445715, 2021). "Firstly, MDSCs contribute to tumor vascularization by producing high levels of matrix metalloproteinase 9 (MMP9), a critical regulator of tumor angiogenesis and vasculogenesis, which releases vascular endothelial growth factor (VEGF) from the matrix." (PMID 35003065, 2021). "MMP-2 and MMP-9 mRNA expressions were enhanced with the increase of the tumor clinical Stages (MMP-2: F = 4.003, p = 0.026, MMP-9: F = 5.501, p = 0.008)." (PMID 31882379, 2021). "Tumor activated macrophages (TAM) are the key inflammatory cells in the tumor stroma that secrete growth factors such as VEGF and MMP-9 with a role in the invasiveness and metastasis of tumor cells." (PMID 33920263, 2021). "Our findings suggest that many of patients who had elevated expression of tumor‐specific signatures such as ESR1, AR, VEGF, AKT1/2/3, CCND1, CDK1, and MMP9 had significantly poorer disease‐free survivals compared with the remaining subgroups." (PMID 33275817, 2021). "Previous studies reported that AFP exerts its tumor promotion through interacting with PTEN, MMP9, and caspase-3 and blocking their functions on the PI3K/AKT, metastasis and caspase signaling." (PMID 33794968, 2021). "Matrix metalloproteinase-2 (MMP-2) and matrix metalloproteinase-9 (MMP-9) are enzymes related to degradation of the extracellular matrix and play an important role in the metastasis of tumours to distant tissues and organs." (PMID 34222329, 2021). "Celecoxib in combination with IFNγ reduced the expression of MMP-2, MMP-9, and VEGF-A in tumor and decreased MVD, mediated by the increased amount of CD68+iNOS+ M1 macrophages and by decreased amount of CD68+Arg1+ M2 macrophages in mouse model of LLC." (PMID 34209679, 2021). "Western blot analysis of tumor tissues showed that MUC1 overexpression partially rescued the effect of YBX1 silencing on CD133, Oct-4, MMP9, E-cadherin, β-catenin, and Snail expression." (PMID 34976785, 2021). "Compared with si-ADAMTS9-AS1 + DMSO group, the expression levels of Ki67, PCNA, MMP-2 and MMP-9 in si-ADAMTS9-AS1 + INCB018424 group were prominently constrained, indicating decreased tumor proliferative activity (p < 0.05)." (PMID 34900984, 2021).
tumor (continued). "Based on the TCGA and GTEx data, we found that MMP1, MMP3, MMP7, MMP9, MMP12, MMP13 all increased in the tumor as compared with the normal esophageal tissues." (PMID 34559117, 2021). "By contrast, MSCs did not present the innate anti-tumor actions but the overexpression of Lrp5 converted them into anti-tumor agents by reducing the MTT-based viability and downregulating MMP9, Runx2, and Snail, as well as N-cadherin in EO771 cells." (PMID 33802279, 2021). "We demonstrated a novel mechanism of tumor invasion and metastasis in NSCLC that involves the activation of the XBP1/IGFBP3/MMP-9 pathway." (PMID 34094948, 2021). "A drastic reduction in the expression of TGF-β1and MMP-9 proteins known to be involved in epithelial to mesenchymal transition (EMT) and tumour cell migration was also observed in CMRP-treated HCT116 cells." (PMID 33436696, 2021). "In BC, numerous subtypes of MMPs containing MMP1, MMP7, MMP9 and MMP11 have investigated a positive correlation between increased levels of MMPs and tumour progression." (PMID 34142438, 2021). "Man-MPs overexpressed MMPs, such as MMP9 and MMP14 proteins, leading to the efficient degradation of tumor collagen." (PMID 33469052, 2021). "TAMs, Treg cells, neutrophils, and mast cells facilitate tumor sprouting angiogenesis by secreting proangiogenic molecules such as VEGF-A, IL-6, IL-8, and MMP-9 to support EC activation, proliferation, and survival." (PMID 34359588, 2021). "Western blot result exhibited that compared with si-NC + DMSO group, the expression levels of Ki67, PCNA, MMP-2 and MMP-9 in si-ADAMTS9-AS1 + DMSO group were markedly boosted, indicating increased tumor proliferative activity." (PMID 34900984, 2021). "In cancer cells, miR-1 works as a tumor suppressor and can target directly or indirectly a plethora of proteins, including MMP-2, MMP-9, and the antiapoptotic protein BCL2, which is considered one of the main targets of the tumor-suppressive action of miR-1." (PMID 34575852, 2021). "High levels of MMP9 have been detected in the invasive tumor frontier (ITF), and many studies have applied MMP9 as a potential marker of invasive OSCC." (PMID 34224327, 2021). "Specifically, activated T‐cell exosomes triggered accumulation of c‐FLIP, a known inhibitor of apoptotic death, in tumour cells thus stimulating the activation of ERK and NF‐κB pathways which in turn contributed to increased expression of MMP9." (PMID 33815694, 2021). "It was shown that 6 cytokines were upregulated more than 2-fold in 4T1 tumor-bearing mice compared to normal mice, namely OPN (osteopontin), CCL12 (chemokine (C-C motif) ligand 12), IL-33, CCL17, CCL6, and MMP-9." (PMID 34771120, 2021). "In this study, we confirmed that MMP9, a critical regulator of ECM and tumor microenvironment, is the direct target of the circUBAP2/miR-194-3p axis." (PMID 34239873, 2021). "When investigating the mRNA expression of COL1A2, POSTN, GREM1, MMP1, and MMP9 in patient material, we found all five genes to be upregulated in HNSCC tumor tissue compared to normal oral tissue." (PMID 34283070, 2021). "ECM remodeling by MMP-9 facilitates release and subsequent activation of VEGF from the ECM, thereby increasing vascularization of the tumor." (PMID 34204306, 2021). "We found that the protein level of MMP2, MMP7, MMP9, MMP12, and MMP14 in the tumor tissue were basically higher than that in the normal tissue." (PMID 34804973, 2021). "Given their importance in tissue remodelling and organ development, abnormal MMP expression (especially MMP‐2, MMP‐9 and MMP‐14) is seen in a host of diseases, from autoimmune disorders to cancers, impacting tumour and immune‐cell microenvironments." (PMID 33675132, 2021). "Compared with the normal mice group, lung section from tumor-bearing mice exhibited enhanced S100A9 and MMP-9 expression on the 14th day." (PMID 34045459, 2021). "MMP9 can also regulate vascular endothelial growth factor (VEGF) expression, an essential factor for angiogenesis and tumor growth." (PMID 33919449, 2021).